NDUFS1 (NADH:ubiquinone oxidoreductase core subunit S1)
Description:
Core subunit of the mitochondrial membrane respiratory chain NADH dehydrogenase (Complex I) which catalyzes electron transfer from NADH through the respiratory chain, using ubiquinone as an electron acceptor. Essential for catalysing the entry and efficient transfer of electrons within complex I. Plays a key role in the assembly and stability of complex I and participates in the association of complex I with ubiquinol-cytochrome reductase complex (Complex III) to form supercomplexes.
Synonyms: CI-75kD; CI-75k; MC1DN5; PRO1304
Tractability: Small molecule: an approved drug acts on it; a structure with a bound ligand is known. Antibody: UniProt places it where antibodies can reach, with medium confidence. PROTAC: ubiquitination databases record sites on it; its protein half-life has been measured.
Target class: Enzyme; Oxidoreductase
Gene: Protein-coding gene on chromosome 2 (206,114,817 to 206,159,522, reverse strand). Ensembl gene ENSG00000023228.
Subcellular location: Mitochondrion inner membrane
Subcellular location (Human Protein Atlas): Mitochondria
Pathways (Reactome):
Metabolism: Complex I biogenesis; Respiratory electron transport
Metabolism of proteins: Mitochondrial protein degradation
Gene Ontology:
Molecular function: NADH dehydrogenase (ubiquinone) activity; protein binding; electron transfer activity; iron-sulfur cluster binding; oxidoreductase activity; oxidoreductase activity, acting on NAD(P)H
Biological process: cellular respiration; mitochondrial electron transport, NADH to ubiquinone; mitochondrial respiratory chain complex I assembly; aerobic respiration; proton motive force-driven mitochondrial ATP synthesis; ATP synthesis coupled electron transport; proton transmembrane transport
Cellular component: mitochondrial inner membrane; mitochondrial intermembrane space; mitochondrion; respiratory chain complex I; mitochondrial matrix; membrane
Genetic constraint (gnomAD): Loss-of-function variants: 52 observed, 78.33 expected, observed/expected ratio (o/e) 0.66, 90% interval 0.53 to 0.84. The upper end of that interval is the gene's LOEUF score, 0.84, which puts it in group 3 of 6, group 1 being the genes least tolerant of losing a copy. Missense variants: 840 observed, 888.11 expected, observed/expected ratio (o/e) 0.95, 90% interval 0.89 to 1. Synonymous variants: 261 observed, 292.66 expected, observed/expected ratio (o/e) 0.89, 90% interval 0.81 to 0.99.
Gene-disease validity (ClinGen):
ClinGen rates the evidence that NDUFS1 causes each of these diseases.
Leigh syndrome (autosomal recessive): Definitive. A progressive neurological disease defined by specific neuropathological features associating brainstem and basal ganglia lesions.
mitochondrial disease (autosomal recessive): Definitive.
Homologues: Orthologues: chimpanzee NDUFS1 (99% identical), macaque NDUFS1 (99% identical), dog NDUFS1 (98% identical), rabbit NDUFS1 (98% identical), pig NDUFS1 (97% identical), guinea pig NDUFS1 (95% identical), rat Ndufs1 (95% identical), mouse Ndufs1 (94% identical), tropical clawed frog ndufs1 (86% identical), zebrafish ndufs1 (81% identical), Drosophila melanogaster ND-75 (63% identical), Caenorhabditis elegans nuo-5 (57% identical). Paralogues in human: NARF (13% identical), CIAO3 (11% identical).
Diseases named in the same sentence as NDUFS1 in open-access papers:
NDUFS1 is named in the same sentence as 97 diseases in open-access papers, as found by Europe PMC text mining. Sharing a sentence is not in itself a finding about the gene and the disease. The quoted sentences say what the papers report.
lung carcinoma (9 papers, 2016 to 2025). "Among the miRNAs in association with lung cancer risk, we further predicted and validated miR‐3130‐5p as an intermediate modulator of risk loci 2q33 and the tumor suppressor NDUFS1." (PMID 33978320, 2021). "Disruption of ETC supercomplexes with MitoTam increased the therapeutic efficacy of mtROS inducing chemotherapeutics in both C92D Ndufs1-knockin or metastatic lung cancer cells." (PMID 40752580, 2025). "Mouse double minute 2 (MDM2) can bind to and sequester NDUFS1 to reduce mitochondrial respiration and increase mROS, ultimately leading to apoptosis in lung cancer cells." (PMID 37644092, 2023). "Recent reports have shown that NDUFS1 expression is very low in lung cancer and renal cell carcinoma." (PMID 37644092, 2023). "Recent studies have shown that the expression of NDUFS1 is downregulated in human lung cancer and renal cell carcinoma, which is closely related to tumor stage, distant metastasis, and poor prognosis." (PMID 37644092, 2023). "We assessed the phenotypic impacts of the interaction between miR‐3130‐5p and NDUFS1 in both lung cancer cell lines and mice xenograft models." (PMID 33978320, 2021). "The in vitro experiments suggest that miR‐3130‐5p functions as a modulator of NDUFS1 with phenotypic impacts in lung cancer." (PMID 33978320, 2021). "The opposite prognostic effect of NDUFS1 and NDUFS8 reflects the oncojanus role of nDNA-encoded core subunits and the panel combining NDUFS1 and NDUFS8 expressions predicts lung cancer prognosis." (PMID 27516145, 2016). "Of these, Aco2, Idh2, Ndufs1, Hadh, Dlat, Itgam, Dlat, Hadha, Mrpl11, Dlst, and Hspd1 show potential as oncoproteins and tumor suppressors and warrant further study for their possible role in inflammation-driven lung cancer." (PMID 40429836, 2025). "Taking together, the panel combining NDUFS1 and NDUFS8 expression could be used to predict the risk of poor prognosis more precisely by reflecting the metabolism status of lung cancer." (PMID 27516145, 2016). "NDUFS1 and NDUFS8 as the leading prognostic factors in 7 nDNA-encoded core subunits can be a useful panel for prognosis prediction and therapeutic decision in lung cancer patients." (PMID 27516145, 2016). "For example, low NDUFS1 and high NDUFS8 expression levels in lung cancer were found to predict poor overall survival." (PMID 35831908, 2022). "Differences in NDUFS1 and ATP5O expression levels have only been described in clear cell renal carcinoma and lung cancer patient samples so far." (PMID 34885151, 2021). "The panel with NDUFS1 and NDUFS8 reflecting tumor metabolism status is a novel prognostic predictor for lung cancer." (PMID 27516145, 2016).
Leigh syndrome (8 papers, 2012 to 2025). "Mutations in the complex I genes NDUFS4 and NDUFS1 commonly lead to Leigh syndrome, an aggressive form of complex I deficiency." (PMID 37399212, 2023). "Mutations in NDUFS1 cause complex I deficiency and Leigh syndrome." (PMID 37399212, 2023). "The m.7979G > A is located in MT-CO2, encoding a subunit of Complex IV, and NDUFS1 encodes a Fe-S protein operating within complex I. Variants in MT-CO2 and NDUFS1 are associated with Leigh syndrome." (PMID 36918699, 2023). "Leukoencephalopathy seems more prevalent in patients with NDUFS1 and NDUFV1 mutations, but mutations in both genes may also lead to Leigh syndrome." (PMID 22644603, 2012). "Moreover, NDUFS1 (NADH:ubiquinone oxidoreductase 75 kDa Fe‐S protein 1) is another member of complex I, its mutations also correlated with various diseases such as diabetic cardiomyopathy, myocardial hypertrophy, schizophrenia, leukoencephalopathy, and Leigh syndrome." (PMID 37029501, 2023).
schizophrenia (7 papers, 2007 to 2023). A major psychotic disorder characterized by abnormalities in the perception or expression of reality. "Lower protein levels of complex I subunits encoding genes NDUFV2 and NDUFS1 were identified in various brain regions of patients affected by Down syndrome or Morbus Alzheimer’s and schizophrenia." (PMID 37508386, 2023). "There was a significant difference in the mRNA level of NDUFV1 (P = 0.003), NDUFV2 (P < 0.01), and NDUFS1 (P = 0.003) between the first-episode schizophrenia patients and control subjects." (PMID 25713723, 2014). "The level of mRNA expression of NDUFV1, NDUFV2, and NDUFS1 was significantly higher in the schizophrenia group than in the control group." (PMID 25713723, 2014). "The mRNA level of NDUFV1, NDUFV2, and NDUFS1 in the first-episode schizophrenia patients was higher than that in the controls, and the mRNA level of NDUFV2 was higher in the chronic schizophrenia patients than in the controls." (PMID 25713723, 2014). "A genetic variant in the NDUFS1 gene was reported to be associated with schizophrenia and negative symptoms in Han Chinese subjects." (PMID 36672898, 2023). "Our results suggest that mRNA levels of the NDUFV1, NUDFV2, and NDUFS1 genes of complex I of the mitochondrial electron transport chain might become a possible peripheral marker for the diagnosis of schizophrenia." (PMID 25713723, 2014). "Mithramycin induced a time dependent decrease in mRNA and protein levels of complex I subunits NDUFV1, NDUFV2 and NDUFS1, as well as of reelin, which was arbitrarily chosen as a gene known to be modulated by Sp1 and repeatedly reported to be abnormally expressed in schizophrenia." (PMID 17786189, 2007). "The present study aimed to investigate the relationship between the clinical features of schizophrenia, and mitochondrial complex activation, based on measurement of mRNA levels in the NDUFV1, NDUFV2, NDUFS1, and UQCR10 genes involved in the peripheral mitochondrial complex." (PMID 25713723, 2014). "In our previous studies, the expression of NDUFS1 was not significantly altered in schizophrenia in the prefrontal and the parieto-occipital cortices and in lymphocytes." (PMID 17786189, 2007). "However, we observed nominal significant associations of 2 SNPs in the NDUFS1 gene and 4 SNPs in the NDUFS2 gene with early onset schizophrenia (EOS), but none of these associations survived the Bonferroni correction." (PMID 26053550, 2015).
colorectal cancer (5 papers, 2021 to 2025). A primary or metastatic malignant neoplasm that affects the colon or rectum. "It is known that PHB2 can interact with NDUFS1 to stabilize the mitochondrial complex I and to enhance its activity in human colorectal cancer cells." (PMID 40828869, 2025). "Oncomine database revealed that NDUFS1 mRNA expression was increased significantly in colorectal cancer, leukemia, lymphoma, melanoma and prostate cancer while was decreased significantly in sarcoma." (PMID 37469574, 2023). "For exploring NDUFS1’s function using gain-of-function strategy, the overexpression of NDUFS1 were used to investigate its role in mediating the radiosensitization of colorectal cancer or in miR-3130-5p mediated invasiveness of lung adenocarcinoma." (PMID 37469574, 2023). "In addition, loss-of-function strategy using siRNA or shRNA mediated RNA interference were used to reveal NDUFS1-mediated colorectal cancer cell proliferation and tumorigenesis, or to study the MDM2-binding associated ROS production, respectively." (PMID 37469574, 2023). "Although studies linking NDUFS1 directly to CC are lacking, research has shown its role in promoting colorectal cancer cell proliferation and tumorigenesis." (PMID 40305445, 2025). "Furthermore, low NDUFS1 and PDH expression were validated to be correlated with poor tumor regression grading (TRG) in local advanced colorectal cancer (CRC) patients underwent neoadjuvant radiotherapy." (PMID 34489398, 2021). "The Kaplan–Meier survival analysis revealed that low expression of NDUFS1, PDP1(rather than PDK1), and PDH, was correlated with poor prognosis respectively in colorectal cancer patients who received radiotherapy." (PMID 34489398, 2021).
Leukoencephalopathy (5 papers, 2012 to 2023). This term describes abnormality of the white matter of the cerebrum resulting from damage to the myelin sheaths of nerve cells. "The homozygous mutation p.Asp252Gly in NDUFS1 alone was shown to cause the disassembly of CI in a patient with mild cavitating leukoencephalopathy." (PMID 31557978, 2019).
non-small cell lung carcinoma (5 papers, 2016 to 2022). A group of at least three distinct histological types of lung cancer, including non-small cell squamous cell carcinoma, adenocarcinoma, and large cell carcinoma. "For example, loss of the mammalian NDUFB10 (pdsw in Drosophila) reduces the growth of K-RAS tumors, whereas low expression of NDUFS1 (which encodes another Complex I subunit) is correlated with poor prognosis and metastasis in non-small cell lung cancer patients." (PMID 33199523, 2020). "Low NDUFS1 expression has been reported to be correlated with poor prognosis in non-small cell lung cancer." (PMID 34489398, 2021). "Studies verified that high NDUFS8 and low NDUFS1 expressions were correlated with poor prognosis in patients and played a leading prognostic role in non-small-cell lung cancer (NSCLC), suggesting that their expressions might predict lung cancer prognosis." (PMID 36557887, 2022). "Similarly, one study found that the NMGs NDUFS1 and NDUFS8 (encoding subunits of mitochondrial complex 1) had significant prognostic power in the patients with non-small cell lung cancer (NSCLC) by analyzed immunohistochemical staining and RNA expression data." (PMID 34760888, 2021). "The results revealed that low NDUFS1 expression and high NDUFS8 expression are correlated with poor prognosis and have leading prognostic roles in non-small cell lung cancer." (PMID 27516145, 2016).
breast carcinoma (4 papers, 2023 to 2025). "The TCGA-BRCA cohort analysis emphasizes a potential interplay of metabolic genes like NDUFS1, TRPM4, ARMCX5, SLCO6A1, and epigenetic axis genes like SETDB1 and USP37 in the oncogenesis and prognosis of breast carcinomas." (PMID 41503337, 2025). "Consistent with these advancements, our analysis reveals SETDB1, NDUFS1, ARMCX5, TRPM4, and SLCO6A1 as significantly altered genes in high-grade breast carcinomas." (PMID 41503337, 2025). "Thus, these analyses uncovered the possible association of the CI functionality—the NAD+‐regenerating capability accompanied by electron transfer by NDUFS1, NDUFS7, and NDUFS8—with cancer progression in patients with HR(+)/HER2(−) breast cancer." (PMID 39873399, 2025). "Using an engineered metastatic niche, we identified a 9‐gene signature (Dhx9, Dusp12, Fhl1, Ifitm1, Ndufs1, Pja2, Slc1a3, Soga1, Spon2) that successfully delineated metastatic breast cancer from nonmetastatic breast cancers including an invasive cell line without metastatic potential." (PMID 38193115, 2024).
diabetic cardiomyopathy (4 papers, 2023 to 2025). Diabetic cardiomyopathy is a disorder of the heart muscle in people with diabetes. "Previous studies on diabetic cardiomyopathy have revealed that AKAP1 down-regulation can compromise mitochondrial respiration by impeding NDUFS1 translocation into mitochondria and promoting mitochondrial ROS generation." (PMID 39469220, 2024).
lung adenocarcinoma (4 papers, 2016 to 2024). A carcinoma that arises from the lung and is characterized by the presence of malignant glandular epithelial cells. "Mir-3130 has been found to inhibit the expression of NDUFS1 to promote the invasiveness of lung adenocarcinoma in vivo and in vitro and could also regulate the miR-3130-3p/NFYA/SATB1 axis to promote the occurrence and development of endometrial cancer cells." (PMID 39591000, 2024).
Myocardial fibrosis (4 papers, 2022 to 2025). "Compared with the control mice, the cardiac Ndufs1-overexpressing mice displayed a reduced infarct size and myocardial fibrosis, as indicated by Masson trichrome staining." (PMID 35817848, 2022). "Indeed, forced expression of Ndufs1 in cardiocytes improves complex I activity and alleviates cardiac dysfunction and myocardial fibrosis." (PMID 37029501, 2023). "Furthermore, we found that cardiac-specific Ndufs1 overexpression alleviates cardiac dysfunction and myocardial fibrosis in the healing phase of MI." (PMID 35817848, 2022). "Ndufs1 overexpression mediated by AAV9 attenuated cardiac dysfunction and myocardial fibrosis during the healing phase of MI." (PMID 35817848, 2022). "Interestingly, Ndufs1 overexpression effectively alleviated cardiac dysfunction in the healing phase of MI and reduced infarct size and myocardial fibrosis but had no significant beneficial effects on cardiac function and structure in the acute phase of MI." (PMID 35817848, 2022).
gastric cancer (3 papers, 2021 to 2024). A primary or metastatic malignant neoplasm involving the stomach. "Recent studies suggested that NDUFS1 has an important role in human cancers; however, the effects of NDUFS1 on gastric cancer (GC) are still not fully understood." (PMID 37644092, 2023). "Mitochondrial dysfunction in cancer has been recognized, and increased NDUFS1 and ATP5O expression has also been described as unfavorable in breast and gastric cancer." (PMID 34885151, 2021).
glioblastoma (3 papers, 2023 to 2025). The most malignant astrocytic tumor (WHO grade IV). "In pan-cancer analysis, the protein level of NDUFS1 was significantly decreased in 6 cancers of breast, colon, pancreas, head and neck, glioblastoma and liver, with decreasing most greatly in ccRCC (KIRC)." (PMID 37469574, 2023). "At the same time, overexpression of NADH: ubiquinone oxidoreductase core subunit S1 (NDUFS1) can enhance the activity of complex I, reverse glycolysis and render tumor cells re-sensitive to radiation, A common metabolic feature in glioblastoma cell lines is reduced mitochondrial reserve capacity." (PMID 40746885, 2025). "Interestingly, oncostatin M, a pleiotropic cytokine belonging to the IL-6 family, may suppress NDUFS1/2 and improve the glioblastoma response to ionizing radiation, thereby prolonging lifespan." (PMID 36675163, 2023).
myocardial infarction (3 papers, 2022 to 2025). Gross necrosis of the myocardium, as a result of interruption of the blood supply to the area, as in coronary thrombosis. "More recently, overexpression of NDUFS1 alleviates myocardial infarction, hypoxia-induced ROS production, and ROS-related apoptosis." (PMID 40828869, 2025). "Here, we show that NADH:ubiquinone oxidoreductase core subunit S1 (Ndufs1) expression is decreased in the hearts of heart failure patients and mice with myocardial infarction." (PMID 35817848, 2022). "Second, we found that Ndufs1 expression was decreased in patients with heart failure, in mice with myocardial infarction, and in hypoxia-treated NRCMs." (PMID 35817848, 2022). "Given the reduced expression of Ndufs1 in both heart tissue samples and NRCMs, we hypothesized that Ndufs1 is strongly involved in the cardiac pathology of myocardial infarction and heart failure." (PMID 35817848, 2022). "Our study suggests that Ndufs1 overexpression through the AAV9 method may be a promising therapeutic strategy for heart failure after myocardial infarction." (PMID 35817848, 2022).
Parkinson disease (3 papers, 2012 to 2019). A progressive degenerative disorder of the central nervous system characterized by loss of dopamine producing neurons in the substantia nigra and the presence of Lewy bodies in the substantia nigra and locus coeruleus. "Of special interest was the classification of “KEGG routes”, where the proteins ATP5A1, ATP5B, NDUFS1, and UQCRC1 participate in both oxidative phosphorylation and diseases such as Parkinson’s, Alzheimer’s, and Huntington’s." (PMID 30678170, 2019).
testicular cancer (3 papers, 2020 to 2024). A primary or metastatic malignant neoplasm that affects the testis. "NDUFS1 has been reported to be under the regulation of RICTOR in testicular cancer patients." (PMID 32942548, 2020). "Similarly, NDUFS1, an oxidative phosphorylation marker, whose mRNA methylation increased 3.2-fold after cryopreservation in our study, was detected at low levels in semen collected from patients with testicular cancer and at high levels in the sperm of infertile men." (PMID 34344298, 2021). "This was in agreement with previous reports, showing a lower expression of NDUFS1 in the sperm of patients affected by non-seminoma testicular cancer before starting any therapy." (PMID 32942548, 2020).